GUCA2A (guanylate cyclase activator 2A)
Description:
Endogenous activator of intestinal guanylate cyclase. It stimulates this enzyme through the same receptor binding region as the heat-stable enterotoxins.
Synonyms: GCAP-I; GUCA2; STARA
Tractability: Small molecule: it has a high-quality binding pocket. Antibody: its Gene Ontology location is reachable by antibodies, with high confidence; UniProt places it where antibodies can reach, with medium confidence; UniProt predicts a signal peptide or a membrane-spanning region.
Gene: Protein-coding gene on chromosome 1 (42,162,690 to 42,164,745, reverse strand). Ensembl gene ENSG00000197273.
Subcellular location: Secreted
Pathways (Reactome):
Digestion and absorption: Digestion
Gene Ontology:
Molecular function: protein binding; guanylate cyclase activator activity; hormone activity
Biological process: signal transduction
Cellular component: extracellular region
Genetic constraint (gnomAD): Loss-of-function variants: 16 observed, 9.07 expected, observed/expected ratio (o/e) 1.76, 90% interval 1.12 to 1.96. That is too few expected variants to judge how well the gene tolerates losing a copy. Missense variants: 143 observed, 119.62 expected, observed/expected ratio (o/e) 1.2, 90% interval 1.04 to 1.37. Synonymous variants: 51 observed, 46.49 expected, observed/expected ratio (o/e) 1.1, 90% interval 0.88 to 1.38.
Homologues: Orthologues: chimpanzee GUCA2A (98% identical), macaque GUCA2A (97% identical), pig GUCA2A (69% identical), rabbit GUCA2A (69% identical), dog GUCA2A (67% identical), mouse Guca2a (67% identical), rat Guca2a (67% identical), guinea pig GUCA2A (59% identical). Paralogues in human: GUCA2B (32% identical).
Diseases named in the same sentence as GUCA2A in open-access papers:
GUCA2A is named in the same sentence as 24 diseases in open-access papers, as found by Europe PMC text mining. Sharing a sentence is not in itself a finding about the gene and the disease. The quoted sentences say what the papers report.
inflammatory bowel disease (6 papers, 2016 to 2023). A spectrum of small and large bowel inflammatory diseases of unknown etiology. "As GUCA2A has been described to be downregulated in inflammatory bowel disease, this study aimed to study GUCA2A and its potential link to NEC, which to our knowledge has not previously been studied." (PMID 37017768, 2023). "It was reported that the down-regulation of GUCA2A was correlated with inflammatory bowel disease and disrupted intestinal homeostasis in mammals." (PMID 35585152, 2022). "Loss of GUCA2A has been seen in CRC and inflammatory bowel disease and may be related to the disturbance of intestinal homeostasis." (PMID 37816854, 2023). "Recently, we reported that GUCA2A, GUCA2B and GUCY2C, plus several steps of the GC-C signaling pathway, are down-regulated in inflammatory bowel disease (IBD)." (PMID 27044258, 2016). "GUCA2A, GUCA2B, and GUCY2C are downregulated in inflammatory bowel disease, which may have implications in inflammatory bowel disease pathogenesis." (PMID 31467713, 2019). "Furthermore, GUCA2A was considered to be important for studies of NEC since it has been described to be involved in suppressing intestinal inflammation, to be downregulated in colorectal cancer and inflammatory bowel disease, and has to our knowledge not yet been studied in NEC." (PMID 37017768, 2023).
colon cancer (4 papers, 2017 to 2023). "Among them, GUCA2A, VIP, and OXTR have been demonstrated to be significantly associated with the prognosis of colon cancer." (PMID 35281839, 2022). "About colon cancer data set DIEXF, GUCA2A, CA7, and IGHA1 key genes with the accuracy of 87.39 and precision of 85.45 were selected." (PMID 29563929, 2017). "By using qRT-PCR, GUCA2A and COL3A1 were examined in colon cancer and rectal cancer." (PMID 37816854, 2023).
colorectal cancer (3 papers, 2020 to 2023). A primary or metastatic malignant neoplasm that affects the colon or rectum. "The down expression of five genes (SLC26A3, GUCA2A, CLCA4, CLCA1, and AQP8) was significantly associated with poor overall survival in colorectal cancer adenocarcinoma patients, and patients with lower expression levels of CLCA1 had poorer disease-free survival rates." (PMID 35693937, 2022). "Therefore, we speculated that GUCA2A affects the development of colorectal cancer by regulating GUCY2C." (PMID 32462020, 2020). "Second: Long-term study of changes in the expression of GUCA2A and COL3A1 genes in a larger number of patients with colorectal cancer." (PMID 37816854, 2023). "First: Examining the expression of GUCA2A and COL3A1 in blood samples, serum, colorectal cancer cell lines, their role with using overexpression and knock-down methods of genes." (PMID 37816854, 2023).
colitis (2 papers, 2012 to 2021). Inflammation of the colon. "Further, Guca2a+ mice resisted barrier disruption and colitis induced by DSS compared to wild-type mice, quantified by weight loss, survival, colon length, and inflammatory cell infiltration disrupting intestinal architecture." (PMID 22384056, 2012). "Like constitutive expression of the native paracrine hormone GUCA2A, oral administration of the bacterial peptide ST enhanced basal barrier integrity and opposed barrier disruption and colitis induced by DSS." (PMID 22384056, 2012). "Following the induction of colitis by DSS, transcript levels of Gucy2c and Guca2a were reduced in both wild type and S839I mice." (PMID 34546338, 2021).
Obesity (2 papers, 2023 to 2024). Accumulation of substantial excess body fat. "We herein show, for the first time, that obesity reduces GUCA2A mRNA and protein expression in the pancreas, and weight loss achieved by sleeve gastrectomy upregulated both GUCA2A and GUCY2C expression." (PMID 37274331, 2023). "A decrease in GUCA2A mRNA and protein expression (both P<0.05) was found in the pancreas of rats with diet-induced obesity, whereas GUCA2B and GUCY2C gene and protein differences fell out of statistical significance." (PMID 37274331, 2023). "Additionally, a recent report on the gastrointestinal peptides proguanylin (GUCA2A) and prouroguanylin (GUCA2B), which play major roles in obesity and satiety, demonstrated a protective effect against lipotoxicity and mitochondrial dysfunction." (PMID 39524892, 2024). "An upregulation of GUCA2A and GUCY2C, but not GUCA2B, was observed in pancreata from rats with diet-induced obesity one month after sleeve gastrectomy." (PMID 37274331, 2023).
rectal cancer (2 papers, 2023 to 2025). A primary or metastatic malignant neoplasm that affects the rectum. "GUCA2A is associated with intestinal health, intestinal permeability, and inflammation, and is used for disease monitoring and treatment guidance, especially for intestinal diseases such as rectal cancer and IBD." (PMID 38814387, 2025). "We performed qRT-PCR for GUCA2A and COL3A1 in colon and rectal cancer." (PMID 37816854, 2023).
carcinoid tumor (1 paper, 2016). A slow growing neuroendocrine tumor, composed of uniform, round, or polygonal cells having monotonous, centrally located nuclei and small nucleoli, infrequent mitoses, and no necrosis. "Similarly, increased Guca2a expression has been seen in fluorescence-activated-sorted EC cells of Mastomys compared with the intestinal mucosa and serum GN is elevated in patients with carcinoid tumors." (PMID 27044258, 2016).
cervical cancer (1 paper, 2019). A primary or metastatic malignant neoplasm involving the cervix. "Aberrantly expressed GUCA2A can be a candidate marker of poor prognosis in patients with CRC, which may be a therapeutic target for precision medicine in cervical cancer." (PMID 31467713, 2019).
colon adenocarcinoma (1 paper, 2023). "Survival analysis by UALCAN database revealed that low expression of GUCA2A was significantly associated with lower survival rates of colon adenocarcinoma patients and low expression of GUCA2A is not significantly correlated with rectal adenocarcinoma’s poor prognosis." (PMID 37816854, 2023).
colorectal adenocarcinoma (1 paper, 2022). The most common type of colorectal carcinoma. "This corresponds well with our findings where we showed that the down expression of GUCA2A may also contribute to colorectal adenocarcinoma carcinogenesis." (PMID 35693937, 2022). "In conclusion, by integrating WGCNA and differential gene expression analysis, our study screened five important survival-related genes (SLC26A3, GUCA2A, CLCA4, CLCA1, and AQP8) and a 3-gene risk model with the potential to predict the prognosis of colorectal adenocarcinoma." (PMID 35693937, 2022).
cystic fibrosis (1 paper, 2025). Autosomal recessive disorder caused by pathogenic variants in the CFTR gene (cystic fibrosis transmembrane conductance regulator), which encodes a chloride and bicarbonate channel expressed in epithelial cells, and follow the diagnosis criteria. "This revealed an additional 67 significantly differentially expressed protein groups between cystic fibrosis patients and healthy individuals, including GUCA2A, ADAMDEC1, and FABP1 (upregulated) and GP2 (downregulated)." (PMID 40425748, 2025).
large intestine neoplasms (1 paper, 2023). "were associated with prevention/protection against large intestine neoplasms, including GUCA2A, CDX2, VDR, VEFGA, GSTM1, HPGD, and PPARG." (PMID 37296943, 2023). "Furthermore, TTI-101 treatment also led to the upregulation of important genes such as GUCA2A, CDX2, VDR, GSTM1, HPGD, and PPARG that have been shown by others to be associated with the prevention of large intestine neoplasms." (PMID 37296943, 2023).
rectal adenocarcinoma (1 paper, 2023). "tool to screen for GUCA2A and COL3A1 expression in multiple cancer types and found that GUCA2A was significantly downregulated in 11 cancer type and COL3A1 was significantly upregulated in 18 cancer type, especially in colon and rectal adenocarcinoma." (PMID 37816854, 2023).
tumor (10 papers, 2007 to 2024). "As a result, tumor progression through the APC pathway involves loss of the hormone GUCA2A that suppresses the tumor-suppressing receptor GUCY2C." (PMID 35907803, 2022). "In contrast, in addition to Clu and Ly6a, the tumor stem cell population of BLM tumors had significant upregulation of differentiation-related genes such as Guca2a, Car1, Cdx2, Car2, and Muc2." (PMID 38893159, 2024). "In the second step, we investigated the upregulated gene (COL3A1) and downregulated gene (GUCA2A) in the tumor and normal samples expression profile in CRC patients using RNA-Seq data and real-time PCR validation." (PMID 37816854, 2023). "Compared with adjacent normal tissues, the expression of GUCA2A in tumor and metastatic tissues was significantly low, and the normal liver and lung tissues had the lowest expression value (P < 0.05)." (PMID 31467713, 2019). "Obviously, GUCA2A was abnormally expressed in tumor tissues and was significantly different in TCGA and GEO databases." (PMID 31467713, 2019). "Interestingly, we showed that knocking down Cdx2 significantly reduced the expression of differentiated lineages-related genes such as Muc2, Atoh1, and Guca2a in BRAF mutant tumor-derived organoids." (PMID 38893159, 2024). "Because Guca2a was expressed in multiple lineages, we computed RNA velocity for Guca2a to calculate its differential RNA splicing kinetics allowing us to determine which lineages display RNA splicing kinetics for the Guca2a transcript in the different tumor types." (PMID 38893159, 2024). "Furthermore, they conducted qPCR analysis and found that GUCA2A is significantly downregulated in tumor and metastatic tissues when compared to adjacent normal tissues." (PMID 37927469, 2023). "This demonstrates that the expression of COL3A1 and GUCA2A can be beneficial as a tumor biomarker." (PMID 37816854, 2023). "GUCA2A were low expressed in both normal and tumor tissues and COL3A1 was positively expressed in both normal and tumor tissues, but significantly stronger in certain tumor tissues." (PMID 37816854, 2023). "Reduces tumor weight, increases the levels of IFN-γ, TNF-α, GZMB and the expression of CLCA3, TFF3, AGR2, Zg16, Pla2g10, Guca2a." (PMID 35548468, 2022). "According to the HPA database, the protein levels of SLC26A3, GUCA2A, CLCA4, CLCA1, and AQP8 in tumor tissues were all significantly lower than that in normal tissues." (PMID 35693937, 2022). "GUCA2A were significantly downregulated in tumor tissues compared with normal tissues (− 0.41-fold, p-value: 0.0007) and COL3A1 were significantly upregulated in tumor tissues comparison with healthy tissues (7.18-fold, p-value: 0.0001)." (PMID 37816854, 2023). "Consistent with the expression of GUCA2A in our study, the expression of GUCA2B was significantly downregulated in CRC tissues and had a relative high weight in the red module, which further indicates that GUCA2A and GUCA2B may play a consistent role in CRC neoplasia." (PMID 31467713, 2019).
cancer (5 papers, 2020 to 2025). A tumor composed of atypical neoplastic, often pleomorphic cells that invade other tissues. "IPA showed significant changes in the expression levels of genes associated with gastrointestinal disease (Abcb1, Guca2a, Muc2, Rag2, Itga6, and Shh), inflammatory disease (Abcb1, Muc2, and Rag2), and cancer (Muc2, Guca2a, and Rag2)." (PMID 33396408, 2020). "The TF-protein NFKB1 (a regulator of GUCA2A, CA4, CEMIP and MS4A12) is a suppressor of inflammation, ageing and cancer." (PMID 36991484, 2023). "Subsequently, GUCA2A was identified as a potential target for gain of function studies, leading to its amplification and cloning into gene constructs featuring both a robust CMV promoter and a cancer-specific MUC1 promoter." (PMID 41960141, 2025).
GUCA2A also shares sentences with these, for which no sentence is quoted: cone-rod dystrophy (2 papers); gastrointestinal disease (2); adenocarcinoma (1); infectious disease (1); intestinal diseases (1); irritable bowel syndrome (1); necrotizing enterocolitis (1); retinal degeneration (1); Retinal dystrophy (1).